EGR2 (early growth response 2)
Diseases named in the same sentence as EGR2 in open-access papers (continued):
Sharing a sentence is not in itself a finding about the gene and the disease.
tumor (continued). "On one hand, EGR2 acts as a tumor-suppressive factor and exhibits anti-cancer effects in certain types of tumors." (PMID 38911380, 2024). "Among them, KLF14 and EGR2 footprints are enriched in PDOX relative to matched PDO, and silencing of KLF14 or EGR2 promoted tumor growth." (PMID 38380561, 2024). "For CRC106, the final tumor masses were 1.46‐ and 1.83‐fold higher in KLF14‐deficient PDOX and 3.26‐ and 2.25‐fold higher in EGR2‐deficient PDOX compared to the scrambled control group." (PMID 38380561, 2024). "We have demonstrated that Egr2/3, expressed in a proportion of exhausted T cells, are essential for anti-tumour immune responses and anti-PD-1 antibody increases Egr2 positive TILs." (PMID 36342511, 2023). "Egr2 and/or 3 have often been detected in exhausted T cells that express high levels of checkpoint molecules in chronic infection and tumours from both animal models and human patients." (PMID 36342511, 2023). "The effects of temozolomide via the LINC00470/EGR2/SOX4 axis on tumor growth as well as apoptosis and autophagy were also evidenced in nude mice." (PMID 36987665, 2023). "Checkpoint blockade increases TIL density in tumours and we have demonstrated that Egr2 and 3 promote TIL proliferation." (PMID 36342511, 2023). "The transcription factors Egr2 and/or 3 have also been detected in TILs from both tumour models and human solid tumours." (PMID 36342511, 2023). "To further clarify the regulation of FTO to EGR2 in vivo, we detected EGR2 expression in tumor tissue." (PMID 37529797, 2022). "Expectedly, EGR2 protein expression level was significantly increased after FTO overexpression in tumor-bearing mice." (PMID 37529797, 2022). "According to our study, upregulated FTO decreased EGR2 methylation level, which promoted the expression of EGR2 and inhibited tumor growth of PCa." (PMID 37529797, 2022). "Here, we show that chronic antigen induces the anergy-associated transcription factor EGR2 selectively within progenitor exhausted cells in both chronic LCMV and tumours." (PMID 33986293, 2021). "Here the authors show that chronic antigenic stimulation in both tumour and infection models induces the expression of EGR2, which drives and stabilises exhausted cell epigenetic and transcriptional identity." (PMID 33986293, 2021). "Overall, these findings are significant as they identify EGR2 as a functionally relevant marker of progenitor exhausted cells within both tumours and chronic viral infection." (PMID 33986293, 2021). "By means of CD38/Egr2 classification, we observed that, in all tumor types, the proportion of M2 TAMs declined after IT, while that of M1 TAMs increased in TC-1- and TC-1/A9-treated tumors." (PMID 34205330, 2021). "qRT-PCR was performed to detect the mRNA levels of EGR2 in 28 GC and adjacent non-tumor normal tissue samples." (PMID 23924943, 2013). "In the Egr2 subnetwork, Egr2 was found to participate in feedforward loops involving the tumor suppressor Hic1 and the miRNAs let-7a and let-7f." (PMID 23387820, 2013). "Anergy is a hyporesponsive state of T cells commonly encountered at tumor vicinity that is mediated by poor co-stimulation in absence of IL-2, a condition that upregulates various anergy related genes cbl-b, egr2, egr3, itch, GRAIL and DGK1α in T cells." (PMID 23785504, 2013). "By bioinformatics analysis, we predicted the tumor-suppressor, early growth response 2 (EGR2), as a putative target of miR-20a." (PMID 23924943, 2013). "EGR2 is a transcription factor that can restrict tumor growth by regulating tumor suppressor pathways like PTEN, but its precise function in LUAD is unknown." (PMID 41583466, 2025). "Furthermore, we found that INHBA protein treatment up-regulated three tumor inhibitory genes, namely EGR2, ERG3, and NR0B1." (PMID 38658971, 2024). "Moreover, at 48 h, tumor lysis was similar in anergic cells treated with Egr2 siRNA encapsulated NP and responsive cells treated with NS siRNA-NP (Fig. EV5B)." (PMID 38637625, 2024).
tumor (continued). "Therefore, we examined the ability of the exhausted NK cells to control tumor growth upon EGR2 gene silencing utilizing the NRG xenograft PDAC model." (PMID 38637625, 2024). "EGR2 may enhance the tumor microenvironment’s responsiveness to treatment by improving T-cell survival and effector function." (PMID 39590310, 2024). "Furthermore, EPHA4, a shared downstream target gene of KLF14 and EGR2, altered tumor sensitivity to MEK inhibitor treatment." (PMID 38380561, 2024). "They identified the zinc finger transcription factor Egr2 and diacylglycerol kinase DGKα as critical regulators of NK cell anergy, with increased expression observed in both ‘anergic’ and ‘exhausted’ NK cells from a xenogeneic tumor-grafted mouse model." (PMID 38886578, 2024). "Interestingly, combination treatment with guadecitabine/ICBs determined a significant increase of M1 (CD38+Egr2-) macrophages, respect to control and ICBs, indicating that triple therapy skews towards pro inflammatory anti-tumor TAM-M1 responses." (PMID 36934257, 2023). "Overexpression of transcription factor EGR2 in VTT indicated its important role in tumor invasion." (PMID 37328520, 2023). "Combinedly, these results indicated that TrkC may be a key mediator in ES tumorigenicity and acts through the upregulation of selected tumor-associated molecular markers, NKX2-2 and EGR2." (PMID 36171207, 2022). "FTO overexpression also significantly inhibited tumor growth and promoted EGR2 protein expression." (PMID 37529797, 2022). "It restrained tumor advancement through regulating EGR2 in NSCLC." (PMID 35874898, 2022). "In this study, we investigated whether the anergy-associated transcription factor EGR2 regulates CD8+ T cell exhaustion in both chronic viral infection and tumours." (PMID 33986293, 2021). "Given that EGR2 has a key role in inhibiting human tumors malignancy, targeting EGR2 may be an effective new therapy strategies for the prevention of tumor progression." (PMID 34130587, 2021). "EGR2 has been demonstrated play a crucial part in tumor development." (PMID 34130587, 2021). "We measured the levels of miR-17-5p and EGR2 in the tumor tissue." (PMID 34130587, 2021). "Moreover, overexpression of LINC01939 exerted its tumor-suppressive effect through increasing the expression of early growth response 2 (EGR2) protein by sponging miR-17-5p." (PMID 30683847, 2019). "Additionally, the regulation of EGR2 expression can control the immune regulatory pathway and avoid the occurrence of tumor immune escape." (PMID 31844579, 2019). "These collectively suggest that PLAU might server as a significant TF promoting PTC progression, while EGR2 might be a tumor suppressor." (PMID 29351231, 2018). "Furthermore, EGR2 protein levels were also down-regulated in GC tissues compared with the non-tumor normal tissue samples." (PMID 23924943, 2013). "In addition, consistent with predicted relationships in this set, experimental studies have demonstrated interactions between the corresponding proteins in neoplasia; for example ABTB1 and EGR2 are mediators of PTEN tumor suppressor function." (PMID 19094230, 2008). "Thus, Egr2 and 3 are important for maintaining anti-tumour responses of exhausted CD8 + TILs." (PMID 36342511, 2023). "Thus, Egr2 and/or 3 are important for exhausted TILs to maintain anti-tumour immune responses." (PMID 36342511, 2023). "Thus, Egr2/3 might be useful as a marker of anti-tumour immune responses and strategies to enhance Egr2 expression in T cells may help to promote anti-tumour immune responses." (PMID 36342511, 2023). "Furthermore, FTO overexpression inhibited PCa tumor growth and EGR2 expression in vivo." (PMID 37529797, 2022). "Tumor specimens exhibited elevated expression of DTX2, SALL1, ZNF93, ZNF146 and ZSCAN16, contrasting with reduced levels of EGR2, GATA2, and ZEB2." (PMID 40647501, 2025).
tumor (continued). "We found that CX3CR1+ macrophages enhanced the expression of the corresponding target tumor inhibitory genes, such as BTG2, EGR2, ERG3, NR0B1, and SDC4, on NR5A1+ tumor cells." (PMID 38658971, 2024). "For CRC187, the final tumor masses of KLF14‐shRNA1, KLF14‐shRNA2, EGR2‐shRNA1, and EGR2‐shRNA2 were 2.84‐, 2.18‐, 2.87‐, and 1.90‐fold higher than control PDOX, respectively." (PMID 38380561, 2024). "In this study, we discovered that, in contrast to TCF-1, Egr2 and 3 were specifically induced in a proportion of CD8 + TILs in multiple human tumours." (PMID 36342511, 2023). "Simultaneous infection of stromal and tumor cells; Upregulation of Fez1 and Pycard; Downregulation of DLL-4, Angiopoietin 2, PECAM, Tie-1, and FOS EGR2, CREB-5, IL-6, Map2K1, CCL22, TIMD4 and CCL19." (PMID 35640930, 2022). "M2 (F4/80+CD38-Egr2+) macrophages, like MDSCs, are immunosuppressive, while M1 (F4/80+CD38+Egr2-) macrophages mediate anti-tumor immune responses." (PMID 35697801, 2022). "Of note, in this study, miR-17-5p was illustrated to negatively modulate EGR2 in TPC-1 cells, further confirming a tumor oncogene role of miR-17-5p." (PMID 34130587, 2021). "Moreover, reduction of EGR2 could reverse anti-tumor effect of miR-17-5p inhibitor in vivo." (PMID 34130587, 2021). "As revealed from the results, lower EGR1, EGR2, and EGR3 levels displayed a relationship to higher SBR grade, NPI, and tumor stage, respectively (p < 0.0001)." (PMID 33614706, 2020). "Other genes similarly regulated include DUSP1, EGR1, EGR2, JUN, and NR4A1, which are components of the TTP-low tumor gene signature, again linking TTP levels and innate immunity." (PMID 25541715, 2014). "Importantly, some of these pathways regulated by Egr2 and 3 were also enriched in Egr2high CD8 + TILs from human tumours." (PMID 36342511, 2023). "Consistent with the findings in human tumours, Egr2 was detected in a proportion of CD8 + TILs, but not peripheral CD8 + T cells." (PMID 36342511, 2023). "In the absence of Egr2/3, the number of TILs is reduced significantly in tumours and TIL proliferative responses are impaired." (PMID 36342511, 2023). "Tcf7 expression was not reduced in Egr2/3-/- TILs from tumour models indicating that Egr2, specifically induced in TILs, has a distinct function in maintaining the function of exhausted T cells." (PMID 36342511, 2023). "By analysing single cell RNA-sequencing data from human tumours, we found that the transcription factors Early Growth Response 2 (EGR2) and 3 were highly induced in TILs, but not peripheral CD8 + T cells, in multiple patient cohorts." (PMID 36342511, 2023). "Collectively, these data suggest that Egr2 and/or 3 are induced concomitantly with checkpoint molecules in exhausted T cells in the tumour microenvironment rather than driving checkpoint molecule expression." (PMID 36342511, 2023). "Inhibition of STAT3 and EGR1, but not MAPK3 and EGR2, significantly abrogated the capacity of tumor cells to form cell-in-cell structures upon incubation with IFNγ-stimulated T cells and with T cell secreted granules." (PMID 36124553, 2022). "We performed qPCR on a subset of genes that were either among the most significant DEGs identified in our analysis of colon organoids of FAP versus healthy subjects and/or were significant in an analysis of either EOCRC tumor datasets: NKD1, EYA2, EGR2, EPDR1 and IGFL1." (PMID 36077675, 2022). "However, expression of other M1/M2 markers (such as CCL2, IL-10, and EGR2) was similar between XO ki and XDH ki tumor infiltrating macrophages." (PMID 31659168, 2019). "Transcription factor binding motif enrichment analysis identifies several immune-related transcription factors, including three exhaustion-related genes (NR4A1, BATF, and EGR2) and VDR, which potentially play an important regulatory role in tumor-reactive CD8+ T cells." (PMID 31892342, 2019).
tumor (continued). "Therefore, the differential binding of KLF14 and EGR2 and expression of downstream EPHA4 impact both tumor growth and drug sensitivity, suggesting that chromatin remodeling in different PDMC may interfere with their ability to predict therapeutic outcomes." (PMID 38380561, 2024). "We showed that the expression of EGR1, EGR2, EGR3, and EGR4 was significantly lowered in HCC specimens in comparison to nontumor specimens, which suggested that members of the EGR family may serve as a tumor suppressor in the progression of HCC." (PMID 36046377, 2022). "Both EGR2 and MEF2B are regulators of cell transcription, and the former was reported to be involved in the epithelial-mesenchymal transition (EMT) pathway, while the latter was differentially expressed between primary tumors and nodal metastasis tumor in HNSCC." (PMID 34504787, 2021). "Similarly, the proportion of CD38+ TAMs was not altered after the addition of anti-CSF-1R in both tumor types in comparison with the original IT, and the number of Egr2+ TAMs only marginally decreased after the addition of anti-CSF-1R into treated mice with TC-1/A9 tumors." (PMID 34205330, 2021). "However, the expression levels of EGR2/4 had no obvious correlation with tumor stages." (PMID 34178038, 2021).
cancer (35 papers, 2010 to 2025). A tumor composed of atypical neoplastic, often pleomorphic cells that invade other tissues. "Further research is needed to gain a deeper understanding of the specific functions and potential therapeutic value of EGR2 in different types of cancers." (PMID 38911380, 2024). "EGR2 is highly expressed in Cancer, Epithelial Cell, Fibroblast, M1 Microphage, and Natural killer T cells." (PMID 37985782, 2023). "In contrast, some studies have suggested that, in different cancer types, early growth response 2 (EGR2) expression is correlated with apoptosis promotion, with the ETM process inhibitor playing a role in this correlation." (PMID 36980175, 2023). "In this study, we have discovered a unique function of Egr2/3 in maintaining anti-cancer responses of exhausted TILs." (PMID 36342511, 2023). "Among the TFs identified here in the response of aggressive CLL lymphocytes, EGR1 and EGR2 are zinc-finger TFs downstream of the Ras/Raf/MAP kinase pathway that is constitutively activated in various cancers and blood malignancies." (PMID 33833385, 2021). "Methylation at CpG islands within the intron of EGR2 has been shown to confer enhancer activity in cancer cells." (PMID 33554857, 2021). "Other transcription factors that bind to G+C sequences and participate in the control of gene expression during cancer development, such as EGR2, N-Myc, or E2F, were among the more represented factors." (PMID 25110883, 2014). "By dissecting diverse cell types comprising the TME, we identified a novel subset of cancer-associated fibroblast, which showed enriched epidermal growth factor receptor (EGFR)-related transcripts including early growth response 1 and 2 (EGR1 and EGR2)." (PMID 35464471, 2022). "EGR2 induces apoptosis in several cancer cell lines, ETV3 contributes to growth arrest, HES1 is involved in DNA interstrand crosslink damage repair and could participate in response to DNA adducts induced by DEN." (PMID 34383828, 2021). "EGR2 knockdown remarkably decreased the anti-cancer effect of miR-17-5p inhibition." (PMID 34130587, 2021). "EGR2 knockdown significantly attenuate anti-cancer function of miR-17-5p." (PMID 34130587, 2021). "Moreover, EGR2 plays a complex role in a variety of cell types as well as the development of cancer." (PMID 28687085, 2017). "Egr2 was highly induced in a proportion of CD8 + TILs in solid tumours from cancer patients and the gene sets enriched in Egr2high CD8 + TILs were associated with activation of T cells indicating that Egr2high TILs may have enhanced effector function compared to Egr2low TILs." (PMID 36342511, 2023). "EGR2 has been shown to promote metastasis by regulating cell migration and the immune status of the microenvironment, whereas ETS1 enhances cancer cell invasiveness by activating EMT- and matrix remodeling-related genes." (PMID 41373733, 2025). "The activity of the pathway is counter-proportionally correlated with cancer-related proteins, like flotillin 2 (FLOT2) or early growth response 2 (EGR2)." (PMID 39188680, 2024). "Levels of EGR2 are relatively low in THCA tissues, but overexpression of EGR2 can prevent the growth and spread of cancer cells." (PMID 38329437, 2024). "Through Pearson’s correlation coefficient analysis (|R2|> 0.3 and P< 0.05), 206 transcription factors were associated with cancer driver gene expression, and DDX3X, JAK1, EGR2, IKZF3, and CCR7 were the five most enriched cancer driver genes." (PMID 34507558, 2021). "Specifically, exposure of rats to PM2.5–10 from LAC for 1–3 months was found to trigger the expression of inflammatory stress- and cancer-related biomarkers, including upregulation of IL16, IL13-Rα1, and EGR2 genes in the brain." (PMID 32211584, 2020). "At last, the mRNA and protein expression of NFAT2, Egr2, FasL, COX-2 and c-myc in carcinoma and adjacent tissues was investigated." (PMID 33023539, 2020). "Compared with adjacent tissues, the carcinoma tissues expressed less NFAT2, Egr2, FasL and more COX-2 and c-myc." (PMID 33023539, 2020).
cancer (continued). "Compared with adjacent nontumor tissues, the mRNA and protein expression of NFAT2, Egr2 and FasL in carcinoma tissues was obviously downregulated and the expression of COX-2 and c-myc was upregulated." (PMID 33023539, 2020). "Compared with adjacent nontumor tissues, the decreased expression of NFAT2 and Egr2 in carcinoma tissues was consistent with its aggression and malignancy." (PMID 33023539, 2020). "The absence of NFAT2 and Egr2 in carcinoma tissues promotes sensitivity and malignancy of HCC." (PMID 33023539, 2020). "Moreover, in agreement with the MVA pathway being regulated by the EWSR1-FLI1/EGR2 axis, the global expression of 16 MVA pathway enzymes, and specifically the 2 rate-limiting genes HMGCR and HMGCS1, was significantly higher in Ewing cell lines as compared with other cancer cell lines." (PMID 35565457, 2022). "However, the expression of EGR2 was not synchronous in different cancers." (PMID 34178038, 2021).